TFF1 (trefoil factor 1)
Diseases named in the same sentence as TFF1 in open-access papers (continued):
Sharing a sentence is not in itself a finding about the gene and the disease.
tumor (continued). "However, since MCF-7-miR-155 cell line maintained an ERα+ phenotype with altered ERα signaling (evident through loss of PgR and high levels of TFF1), we next sough to determine the correlation between Rictor and PgR in a luminal B tumor subtype." (PMID 25283550, 2014). "Furthermore, a number of interferon (IFN) response genes (BST2, CD74, HLA-DMA, HLA-DPB1, HLA-DQB1, HLA-DRA, HLA-DRB1, and IRF8) were upregulated in C10 compared to the other clusters, whereas genes associated with tumor suppression and apoptosis (TFF1 and TFF2) were downregulated." (PMID 37370788, 2023). "The molecular mechanisms underlying the TFF1 tumor suppressor functions remain unclear." (PMID 25015107, 2014). "Co-expression of TFF1 and S100P has been linked to airway dissemination in NSCLC, indicating their roles in promoting tumor progression." (PMID 40787454, 2025). "TFF1 is considered a gastro-specific tumor suppressor as Tff1KO mice spontaneously develop adenomas in the gastric antral/pyloric mucosa, and approximately 30% of these progress to carcinoma." (PMID 41573568, 2025). "Tumour cells with high TFF1 expression (MP2 state) were clustered mainly at the top of the mucosal layer, while MUC6‐positive cells (MP6 state) were predominantly aggregated around the neck of the gland lumen." (PMID 40292733, 2025). "Tumor-specific deep crypt secretory cells (tDCS, cluster 10) demonstrated elevated expression of TFF1, FABP1, CKB, PRAP1, IL32, GPRC5A, and SOD3, and were consistent with secretory lineage plasticity and immune or stress-associated signaling." (PMID 41282138, 2025). "Tumor tissues exhibited substantial upregulation of TFF1, UBE2C, ITPKA, and IGFBP3, alongside concurrent downregulation of SELENBP1 and SLC34A2, relative to matched normal samples." (PMID 40787454, 2025). "Mechanistically, we previously reported that the tumor-suppressive function of TFF1 in pancreatic and liver carcinogenesis involves the inhibition of Wnt pathway activation." (PMID 40940735, 2025). "In vivo, combined treatment of gemcitabine and subcutaneous administration of TFF1 arrested tumor growth in xenograft mouse model and resulted in the better survival of KPC mice by inhibiting EMT and cancer stemness." (PMID 38872370, 2024). "The subcutaneous administration of TFF1 has been recorded to suppress tumor growth in vivo, affirming that TFF1 enters the bloodstream to reach tumor cells, where it functions as a tumor suppressor." (PMID 39628866, 2024). "Similar to the previous findings, TFF1’s validation with a fold change of 2.8 confirmed its role in tumor cell invasiveness through EGFR signaling and G-protein-coupled receptor pathways." (PMID 39839775, 2024). "Nevertheless, further investigations are needed to clarify the precise mechanisms of the tumor‐suppressive role of TFF1." (PMID 38872370, 2024). "In contrast, C1 and C3 exhibited overexpression of trefoil factor family genes (TFF1, TFF2, and TFF3), which are associated with angiogenesis, apoptosis, and tumour progression." (PMID 37994257, 2024). "The successful analysis of 16,817 tumors from 149 tumor types and subtypes resulted in a comprehensive overview on the expression of TFF1 in human tumors." (PMID 39410561, 2024). "Upregulation in multiple tumor entities and the significant link between TFF1 expression and parameters of malignancy in several tumors argue for a relevant biological role of TFF1 in cancer, however." (PMID 39410561, 2024). "TUNEL staining results indicated a significant increase in the proportion of apoptotic cells in the TFF1 knockdown group, further corroborating the critical role of TFF1 in tumor cell survival." (PMID 39539551, 2024). "Further experiments are needed to reveal the precise mechanisms of TFF1 as a tumor suppressor in various organs." (PMID 38872370, 2024).
tumor (continued). "This structure renders TFF1 resistant to both acid and enzymatic breakdown, and thus perhaps responsible for the ability of TFF1 to inhibit tumor growth in the gastrointestinal tract (GIT)." (PMID 39628866, 2024). "We previously discovered that TFF1 overexpression in RB leads to anti-tumorigenic effects, suggesting a potential tumor suppressor role of TFF1 in this tumor entity." (PMID 38730608, 2024). "The primary T14 tumor cells were also strongly positive for the RB markers synaptophysin and TFF1 as well as for vimentin." (PMID 39695086, 2024). "The miR-18a/low tumours had higher expression of the luminality-associated genes like ESR1, GATA3, FOXA1, XBP1 and TFF1 and a lower expression of the basality-associated genes such as KRT18, KRT17, FOXC1, ANLN, STIL and MIA (p < 0.05)." (PMID 38786043, 2024). "Immunohistochemical analysis showed a substantial reduction in the proportion of Ki67-positive cells in tumors from the TFF1 knockdown group, suggesting that the proliferative capacity of the tumor cells was suppressed." (PMID 39539551, 2024). "At a first glance, a potential tumor suppressor function of TFF1 and elevated expression levels in more advanced, higher-metastasizing RB tumors seem to be conflicting." (PMID 38730608, 2024). "The marker set analysis showed that T18_IM cells express all markers analyzed except for TFF1, only expressed by the original tumor." (PMID 39695086, 2024). "Of note, combined treatment with gemcitabine and shTFF1 almost arrested the growth of the tumor, supporting the possibility of combined treatment with TFF1 and traditional chemotherapy." (PMID 38872370, 2024). "TFF1-expressing (TFF1-positive; TFF1+) RB tumor cells, by contrast, showed significantly increased GIPR expression compared to TFF1-RB tumor cells and compared to hRet." (PMID 38730608, 2024). "Overall, 65 (43.6%) of 149 tumor categories showed detectable TFF1 expression, with 32 (21.5%) tumor categories containing at least one case with strong positivity." (PMID 39410561, 2024). "In vivo studies further demonstrated that TFF1 knockdown slowed subcutaneous tumor growth in mice, decreased the proportion of Ki67-positive cells, and increased the number of TUNEL-positive cells." (PMID 39539551, 2024). "Trefoil factor 1 (TFF1) is a marker of ER responsiveness and is related to tumor invasion and angiogenesis; hence its use as a diagnostic marker of various diseases, including cancer." (PMID 39081245, 2024). "The ranking order of 65 tumor entities according to their rate of TFF1 positivity is a key result of our study." (PMID 39410561, 2024). "In particular, recurrent EGFR-amplified tumours showed increased expression of ZIC2, which is involved in increased cell proliferation, and increased expression of TFF1, which is involved in tumour cell migration." (PMID 36765632, 2023). "Remarkably, all tumors displaying detectable TFF1 in the AH samples also stained positive for TFF1 in the primary tumor sections." (PMID 37835522, 2023). "Using a specific, highly sensitive TFF1 ELISA allowed us to confirm that RB tumor cells secrete soluble TFF1 into the aqueous humor of RB patients’ eyes." (PMID 37835522, 2023). "We therefore analyzed primary RB tumor cells and compared their endogenous TFF1 expression status and ability to secrete TFF1 into the supernatant with RB-tumor-derived stromal cells." (PMID 37835522, 2023). "If this holds true, TFF1 expression is a direct indicator for residual-therapy-surviving and TFF1-secreting tumor cells." (PMID 37835522, 2023). "The intracellular TFF1 expression pattern closely correlated with the TFF1 secretion status observed in the RB tumor cells and RB-tumor-derived stromal cells." (PMID 37835522, 2023).
tumor (continued). "The first AH sample of the tumor with the highest AH TFF1 concentration (T44) observed in our study was received from the clinics after two IVC cycles with melphalan." (PMID 37835522, 2023). "In this case, TFF1 would be an extraordinarily helpful marker for monitoring residual RB tumor cells." (PMID 37835522, 2023). "The subsequent immune histochemical (IHC) staining assay was also conducted, and the protein level of TFF1 between the tumor and normal tissues was detected." (PMID 36428568, 2022). "Based on the survival analysis, the TFF1/TFF2 high-expressed cohort presented favorable overall survival (OS) and tumor-free survival (TFS) as compared to the TFF1/TFF2 low-expressed cohort." (PMID 36428568, 2022). "BPAF at 20 mg/kg bw/day significantly only up-regulated the gene expression of Akt and TFF1 in hypothalamus, while the mRNA expression of the other 17 genes did not present a significant difference relative to SK-BR-3 bearing tumor control." (PMID 36497816, 2022). "We wished to identify such tumor suppressor/s, and found that trefoil family factor 1 (TFF1) was involved in L1-mediated CRC progression." (PMID 36139637, 2022). "In group II tumors, TFF1 expression in the original tumor specimens correlates with the TFF1 expression in the AH." (PMID 35158945, 2022). "We showed that all tumors with detectable TFF1 in the AH samples analyzed stained highly or moderately positive for TFF1 in primary tumor sections." (PMID 35158945, 2022). "We found that TFF1, a protein involved in protecting the mucus epithelial layer of the colon, is downregulated in L1-expressing cells and displays characteristics of a tumor suppressor." (PMID 36139637, 2022). "By adopting this approach, we identified trefoil family factor 1 (TFF1) as a potential tumor suppressor in L1-mediated CRC progression." (PMID 36139637, 2022). "In EC, DSCAM-AS1 was associated with endometrial tumor promotor gene PRL and with expression of ERα and its target genes TFF1 and PGR." (PMID 35885035, 2022). "Nine out of fifteen AH patient samples exhibited TFF1 expression, which correlated well with TFF1 levels of the original tumor." (PMID 35158945, 2022). "Subsequently, we investigated if corresponding primary cell culture cells established from the original patient tumor samples also secrete TFF1 into the cell culture supernatant." (PMID 35158945, 2022). "The results were correlated with the TFF1 expression status in the tumor of origin and compared to TFF1 expression in established corresponding primary tumor cell cultures and supernatants." (PMID 35158945, 2022). "Evaluating TFF1 staining of tumor sections after enucleation, we and others already described TFF1 as a biomarker for a subset of RBs." (PMID 35158945, 2022). "In the study presented, we investigated TFF1 expression in AH via ELISA and Western blot and correlated the expression patterns with clinical parameters and TFF1 expression in the original tumor tissue of the enucleated patients’ eyes." (PMID 35158945, 2022). "Here, we analyzed AH, tumor of origin, and established corresponding primary cell culture cells of 15 RB patients for TFF1 expression and secretion status and compared the results with the clinical parameters." (PMID 35158945, 2022). "TFF1 exhibits anti-inflammatory properties, and its involvement as a tumor suppressor gene has been shown through studies using the Tff1-knockout (Tff1-KO) mouse model." (PMID 35884586, 2022). "TFF1 is expressed in a subpopulation of RB tumors and seems to be correlated with more advanced tumor stages." (PMID 35158945, 2022). "Here, I will discuss recent progress obtained in the field of gastric self-renewal from stem and precursor cells that has developed since 2015 and provide an update concerning the role of Tff1 as an antral tumor suppressor." (PMID 35628183, 2022). "Studies in CRC tissue have detected both a pro-tumorigenic effect and tumor-suppressive effects of TFF1 in CRC." (PMID 36139637, 2022).
tumor (continued). "Among the genes whose levels were upregulated under these conditions, we identified TFF1, which was reported to act as a tumor suppressor in some studies." (PMID 36139637, 2022). "Possibly, primary RB cells expressing TFF1 have a growth advantage in culture that leads to a higher concentration of TFF1 in the cell culture supernatant in comparison to the investigated AH samples of the original tumor specimens." (PMID 35158945, 2022). "The results indicated that the TFF1 CpG island in cg01886855 and cg02643667 were highly methylated in tumor samples." (PMID 36428568, 2022). "Among these, TFF1 plays a crucial role and is considered a gastro-specific tumour suppressor since Tff1KO mice spontaneously develop adenomas in gastric antral/pyloric mucosa and about 30% progress to carcinoma." (PMID 36514982, 2022). "The involvement of TFF1 in tumor progression has been reported for various types of cancer, but its role in L1-dependent CRC development has not been determined." (PMID 36139637, 2022). "In human CRC tissue, TFF1-positive staining was evident in goblet cells of the normal mucosa, while in CRC tissue, TFF1 expression was lost in >50% of the tumor samples." (PMID 36139637, 2022). "Overall, these results showed that while the normal colonic mucosa displayed the presence of TFF1 in goblet cells, in 50% of the samples the adjacent tumor tissue had lost the expression of TFF1." (PMID 36139637, 2022). "We wished to explore the possibility that TFF1 acts as a tumor suppressor during L1-mediated CRC progression." (PMID 36139637, 2022). "The results outlined the role of TFF1 as a tumor suppressor in L1-mediated CRC development—a role which can be developed as a potential therapeutic target for CRC." (PMID 36139637, 2022). "We also found that TFF1 expression in metastases was equal to or greater than that of the primary tumor." (PMID 34679875, 2021). "The most upregulated genes in PDAC include SPINK1, known for contributing towards increased tumor proliferation and poor cancer prognosis; TFF1, which facilitates PDAC metastasis; and S100A6, a key diagnostic marker for PDAC." (PMID 35178072, 2021). "IL17RB activates multiple chemokine (such as CCL20/CXCL1/IL8/TFF1) expressions to enhance tumor cell invasion, macrophage, and endothelial cell recruitment at primary sites and cancer cell survival at distant organs." (PMID 34724890, 2021). "Tanaka and colleagues found, in a series of 182 human GCs, that low expression of TFF1 was significantly correlated with deeper invasion of the tumor." (PMID 34679875, 2021). "OLFM4, SPINK8, CRYAB, KCNMA1, TFAP2B, and TFF1 were significantly upregulated during tumor progression in P8‐2 CTCs." (PMID 33377642, 2020). "This is a further step in order to understand the molecular function of Tff1, in particular as a tumor suppressor." (PMID 31963721, 2020). "The results revealed that conditional Myh9 knockout significantly decreased tumor incidence and prolonged survival of Tff1-/- mice, when compared with the control littermates." (PMID 32685004, 2020). "This resulted in the expression of the pro-inflammatory cytokines and chemokines CCL20, CXCL1, IL-8, and TFF1 leading to the recruitment of macrophages in the tumor microenvironment and of vasculogenic endothelial cells to promote angiogenesis." (PMID 32373132, 2020). "We found that the tumor incidence in Myh9fl/fl; Atp4b-cre; Tff1-/- mice was significantly reduced (5/20, 25%) and the tumor size was smaller, when compared with Myh9fl/fl; Tff1-/- mice (8/20, 40%)." (PMID 32685004, 2020). "The results showed that conditional hMYH9 overexpression significantly increased tumor incidence but reduced mouse survival of Tff1-/- mice, when compared with the control littermates." (PMID 32685004, 2020). "TFF1 is a well-known gastric-related tumor suppressor gene, whereas the function of TFF2 in GC is relatively less investigated." (PMID 32122390, 2020).
tumor (continued). "Accordantly, the IHC analysis also suggested that the proliferative marker Ki67 and the mesenchymal marker N‐cadherin were reduced, whereas the epithelial E‐cadherin was enhanced in tumours with downregulated circ‐TFF1." (PMID 31961997, 2020). "Therefore, loss of Tff1 or Tff2 expression (TFFs peptides) could lead to tumor growth." (PMID 32231118, 2020). "In agreement, shRNA-mediated of CCL20, CXCL1, or TFF1 depletion in CFPAC-1 pancreatic cancer cells significantly decreased the percentage of macrophages that interact with tumor cells in vivo, while IL-8 depletion reduced CD31+ endothelial cell recruitment." (PMID 32373132, 2020). "Meanwhile, we explained that the expression of circ‐TFF1 and TFF1 was reduced while that of miR‐326 increased in tumours from mice with circ‐TFF1‐downregulated BT‐549 cells compared to their levels in those from mice inoculated with control cells." (PMID 31961997, 2020). "Here, we demonstrate that miR-632 promotes tumour angiogenesis and endothelial recruitment in a TFF1-dependent manner." (PMID 30612555, 2019). "Several recent reports indicate that loss of TFF1 expression and its mucosal protective capacity mediate activation of oncogenic pathways, suggesting that TFF1 has tumor suppressor functions in gastric mucosa." (PMID 31292446, 2019). "As a consequence, the role of TFF1 in cancer is still under debate because of its different expression and controversial behavior in various tumor contexts." (PMID 29997345, 2018). "Initially found in breast cancer cells, in this tumor type, TFF1 was indicated as an oncogene in some papers and as a predictive factor of positive response to hormone therapy in some others." (PMID 29997345, 2018). "The purpose of our study was to explore the role of TFF1 in EMT and hypoxic conditions, processes inherently linked to inflammation, and tumor progression." (PMID 29997345, 2018). "TFF1 expression was higher in tumours that express oestrogen receptors (Mann–Whitney U test, P=0.000) and progesterone receptors (Mann–Whitney U test, P=0.004)." (PMID 25900183, 2015). "We validated the in vitro data using a xenograft mouse model, showing that tumor growth was significantly suppressed in TFF1 xenografts as compared to control." (PMID 25015107, 2014). "Correspondingly, the average tumor weight In TFF1 group was decreased by 86% (p<0.01) relative to control nude mice group." (PMID 25015107, 2014). "Briefly, we injected subcutaneously AGS cells stably expressing TFF1 or pcDNA empty vector into the flank regions of female athymic nude mice, and tumor growth was monitored." (PMID 25015107, 2014). "The role of TFF1 in tumorigenesis is controversial, but it is a marker of cellular differentiation, and in some contexts has tumor suppressive activity." (PMID 23390495, 2013). "The combination of FTS and MPA, by reducing the mRNA expression of ERα-mediated genes (i.e. PR, c-fos and ps2/TFF1), inhibited tumor growth and enhanced the death of type 2 EC cells." (PMID 23530112, 2013). "The trefoil factor family proteins (TFF1, 2, 3), regulate mucosal repair and suppress tumor formation in stomach." (PMID 23217022, 2012).